GFAP (glial fibrillary acidic protein)
Diseases named in the same sentence as GFAP in open-access papers (continued):
Sharing a sentence is not in itself a finding about the gene and the disease.
dementia (continued). "Increased GFAP concentrations have been detected in CSF and blood of AD patients, with rising levels already at the preclinical phase of the disease, as well as an association between GFAP levels and cerebral amyloid pathology, brain atrophy, cognitive decline, and future conversion to dementia." (PMID 36072480, 2022). "Based on previous research, we hypothesized that higher GFAP levels would associate with poorer cognition, smaller total brain and hippocampal volume, and increased risk of incident dementia." (PMID 36056631, 2022). "Levels of GFAP-reactive astrocytes are closely associated with dementia in AD." (PMID 34267657, 2021). "After the confirmation of BACE1 and GFAP expressions in the hippocampus, we assessed if both proteins presented association by co-immunoprecipitation, how it had been reported previously and if presented differential association between dementias." (PMID 34025357, 2021). "We hypothesized that reactive astrocytes in frontal cortical areas of PD brains are associated with the occurrence of dementia, and that this is reflected in GFAP and vimentin levels in the CSF." (PMID 22577599, 2012). "GFAP, which is highly correlated with cortical atrophy and cerebral amyloid accumulation, has demonstrated strong diagnostic performance in distinguishing symptomatic from asymptomatic individuals and shows a significant increase in those progressing to dementia." (PMID 40740212, 2025). "GFAP elevation has also been observed in the preclinical phase of AD, and a large-scale study from the UK Biobank recently demonstrated that higher plasma levels of NfL and GFAP were associated with increased risk of all-cause dementia, including AD, FTD, and vascular dementia." (PMID 41206819, 2025). "Additionally, blood biomarkers, including Aβ, p‐tau, NfL, and GFAP, are measured to assess their utility in predicting dementia risk, as well as the predictive performance of the combination of blood biomarkers and cognitive function for diagnosing dementia." (PMID 40760693, 2025). "We found fairly similar results for GFAP and NfL in the association of the neurodegenerative biomarkers with dementia in both countries; those with higher levels of GFAP and NfL were more likely to have dementia both in the individual models and the combined models in both countries." (PMID 40838581, 2025). "Among them, peripheral glial fibrillary acidic protein (GFAP) and neurofilament light chain (NfL) have gained much traction for their ability to predict the risk of dementia in individuals with subjective cognitive decline and mild cognitive impairment, as well as dementia-specific mortality." (PMID 38735950, 2024). "As for GFAP, the prognostic and diagnostic role of serum Nfl has been investigated: elevated levels were identified in many pathologies such as Huntington’s chorea, spinal cord lesions, neurodegenerative diseases such as multiple sclerosis, Parkinson’s and Alzheimer’s, and various forms of dementia." (PMID 36769380, 2023). "Overall, the findings suggest that elevations in circulating GFAP may occur early in the neurodegenerative disease process, highlighting the potential utility of the biomarker for aiding dementia risk prediction and improving stratification in clinical trials targeting the preclinical disease stage." (PMID 36056631, 2022). "Overall, the results provide supportive evidence for the potential value of blood‐derived GFAP as a prognostic marker for incident dementia risk in population‐based settings, which may have use for aiding stratification in clinical trials targeting the preclinical disease stage." (PMID 36056631, 2022). "However, it must also be noted that while GFAP may be associated with other dementias and neurodegenerative disorders, our data clearly show a significant positive association between GFAP and brain Aβ load measured by PET, a gold standard biomarker for AD." (PMID 33431793, 2021).
dementia (continued). "However, we could confirm the earlier reported correlation of an increase in GFAP and vimentin in grey matter with increasing age and the association of α-synuclein pathology in the frontal cortex with LB-related dementia." (PMID 22577599, 2012). "In detail, p-tau217 showed significant difference between CU and dementia (p < 0.01) and both NfL and GFAP showed significant difference both between CU and MCI and CU and dementia." (PMID 41282064, 2025). "In conclusion, key dementia blood biomarkers GFAP and NEFL are differentially impacted by genetic risks for AD, pointing to gene specific pathways to neurodegeneration." (PMID 40061357, 2025). "For MCI patients who progressed to any form of dementia, plasma GFAP contributed on top of age, sex, and MMSE score in the parsimonious individualized prognostic model (C-index = 0.69 [95%CI = 0.63; 0.76])." (PMID 41339948, 2025). "Previous studies evaluated the ability of plasma pTau181, NfL, and GFAP to discriminate among different dementias." (PMID 40847319, 2025). "This study demonstrates the potential of plasma biomarkers, especially pTau217, GFAP, and NfL, as noninvasive tools for dementia diagnosis and differentiation." (PMID 40613333, 2025). "Because of this early and sustained increase in GFAP levels, plasma GFAP has excellent prognostic value for conversion to dementia." (PMID 39289040, 2025). "A higher standardized GFAP increased the relative likelihood of having dementia by 45% for the individual model in LASI-DAD and 67% for the individual model in HRS." (PMID 40838581, 2025). "This study investigated the association between high-impact genetic variants in APOE and TREM2 and plasma levels of GFAP and NEFL in the context of incident dementia among the over 50,000 UKB participants." (PMID 40061357, 2025). "Higher plasma levels of GFAP and NfL have been associated with more MTA in Aβ-positive patients with subjective cognitive impairment, mild cognitive impairment and dementia, as well as with CVD in incident dementia." (PMID 40847319, 2025). "In contrast, increased serum GFAP levels have shown correlations with immunohistochemistry-based astrocytic reactivity and post-mortem brain atrophy in dementia patient cohort study." (PMID 40346659, 2025). "Third, increasing levels of plasma NfL and GFAP were associated with decreasing cognitive composite scores and increased odds of our cognitive impairment outcome (MCI or probable dementia)." (PMID 39913137, 2025). "Among participants who developed dementia, APOE4 is significantly associated with GFAP after controlling for time to dementia diagnosis (Beta = 0.175, P = 2.4e-11)." (PMID 40061357, 2025). "In the full model including all plasma biomarkers, GFAP and MMSE score were the only variables which remained significantly associated with any-cause dementia risk." (PMID 41339948, 2025). "Cases with dementia had marginally higher concentrations of p-tau217 (p = 0.06) and higher concentrations of GFAP and NfL (p < 0.05) than cases with NC." (PMID 41384822, 2025). "Participants who were Aβ+ had greater rates of dementia and a higher prevalence of carrying the APOE ε4 allele; had lower MMSE scores; and had greater levels of plasma p‐tau217, p‐tau181, and GFAP." (PMID 39877979, 2025). "Single biomarkers discriminated well between dementia patients and controls: the Aß42/40 ratio (AUC:0.86) or GFAP (AUC:0.83) was found for AD, and the NfL (AUC:0.84) was found for FTD patients." (PMID 39940998, 2025). "Reactive astrocytes have been linked to neuroinflammation in AD patients that precedes Aβ plaques, with clinical studies showing a significant increase in peripheral blood GFAP levels in dementia patients compared to healthy controls." (PMID 41306424, 2025). "With AD-dementia as the outcome, GFAP and pTau181 were selected in the parsimonious model on top of the demographic variables (C-index = 0.71 [95%CI = 0.65; 0.76])." (PMID 41339948, 2025).
dementia (continued). "An increased Recombinant human GFAP has been reported as a biomarker for AD-related pathogenesis prior to dementia." (PMID 40867161, 2025). "We observed significant associations of both GFAP and NEFL with future all-cause dementia in the UKB participants." (PMID 40061357, 2025). "Similar to CSF findings, plasma GFAP is elevated across multiple neurodegenerative diseases, including frontotemporal dementia, Parkinson’s disease dementia, dementia with Lewy bodies, and AD." (PMID 40690136, 2025). "Clinical studies show that the increased expression of blood GFAP can be used as an optimal biomarker for dementia prediction, more than 10 years before diagnosis." (PMID 40806404, 2025). "NfL was associated with incident diagnosis of several neurodegenerative diseases, while GFAP was specific to AD, reinforcing its role in dementia." (PMID 41206819, 2025). "Key blood biomarkers for dementia include phosphorylated-tau-217, phosphorylated-tau-181, amyloid beta 1–42/1–40, glial fibrillary acidic protein and neurofilament light." (PMID 41339948, 2025). "Higher levels of both GFAP and NEFL in midlife are significantly associated with greater risk for incident dementia." (PMID 40061357, 2025). "A recent breakthrough study has identified GFAP as a potential biomarker for dementia, with changes in its expression observed at least ten years prior to the onset of the disease." (PMID 40832351, 2025). "Our findings highlight that GFAP or pTau217 alone have utility for prediction of dementia, and combining pTau and GFAP adds specificity for AD dementia prognosis." (PMID 41339948, 2025). "We then used a backward time scale to observe the trajectory of GFAP and NfL levels prior to the onset of dementia." (PMID 38735950, 2024). "Compared to using age alone as the predictor for dementia, incorporating GFAP and NfL improved the NRI for predicting all-cause dementia, ADRD, and VD (NRI = 0.012 to 0.088)." (PMID 38735950, 2024). "The elevated GFAP and NfL levels in the intermediate tertile likely represent individuals at higher risk of progressing to MCI/dementia due to elevated AD and VCID pathologies." (PMID 37932910, 2024). "Neurofilament light (NfL), glial fibrillary acidic protein (GFAP), and total tau (t-tau) are promising fluid biomarkers with the potential for identifying pathological processes underlying dementia." (PMID 37530894, 2024). "Considering that one of the neuropathological hallmarks of HIV‐1‐associated dementia (HAD) is the proliferation of astrogliosis, it is expected that a strong association between higher GFAP and NCI/HIVE should exist." (PMID 38282400, 2024). "We investigated the associations of plasma neurofilament light (NfL), glial fibrillary acidic protein (GFAP), and total tau (t-tau) with markers of cerebral small vessel disease (SVD) and with incident dementia." (PMID 37530894, 2024). "In conclusion, we successfully developed and validated a result visualization and interpretation tool for a neurocognitive blood test including the markers P‐tau181, GFAP, and NfL, which is ready for testing in the real‐world clinical dementia settings." (PMID 39096164, 2024). "This was a prospective cohort study to evaluate UK Biobank participants enrolled from 2006 to 2010 using plasma GFAP and NfL measurements measured by Olink Target Platform and prospectively followed up for dementia diagnosis." (PMID 38735950, 2024). "Here, we evaluated the role of plasma GFAP, NfL, and pTau 181, combined together, as biomarkers for the early diagnosis of AD and for the assessment of progression to dementia." (PMID 38654932, 2024). "The review revealed that the non-specific elevation of NfL was found in nerve injury diseases beyond dementia, while GFAP was more relevant to Aβ deposition." (PMID 38352136, 2024).
dementia (continued). "More importantly, these individuals not only demonstrated enhanced cognitive functioning and lower GFAP and NfL levels but also remained free of any dementia diagnosis throughout the duration of the study." (PMID 38735950, 2024). "Elevated levels of GFAP have also been detected in the serum of patients with various types of dementia, traumatic brain injury, epileptic seizure, Parkinson’s disease, multiple sclerosis, and spinal cord injury." (PMID 38352136, 2024). "GFAP and NfL significantly improved the predictive values for dementia using previous models (area under the curve (AUC) ranges from 0.80 to 0.89, C-index ranges from 0.86 to 0.91)." (PMID 38735950, 2024). "The large sample size bolsters the evidence supporting peripheral GFAP and NfL as early biomarkers of dementia." (PMID 38735950, 2024). "The best model for predicting all-cause dementia, ADRD, and VD was DRSm combined with GFAP and NfL, with corresponding AUC of 0.867, 0.892, and 0.892 respectively, and corresponding C-Index of 0.871, 0.904, and 0.910." (PMID 38735950, 2024). "Previous studies that have identified GFAP and NfL levels as prognostic factors for dementia typically involved much longer follow-up durations, ranging from 4 to 14 years." (PMID 39297507, 2024). "Over a decade-long follow-up period, we observed elevated GFAP and NfL levels even before dementia diagnosis." (PMID 38735950, 2024). "In our study, peripheral GFAP and NfL levels were notably effective in distinguishing participants with dementia from others, corroborating the findings of previous studies." (PMID 38735950, 2024). "GFAP is considered a potential biomarker for the early diagnosis of dementia and AD, in line with our findings." (PMID 39273422, 2024). "In contrast, both pTau217 and GFAP saw a significant decrease in the percentage of saved tau-PET scans when requiring 90% or 95% sensitivity and looking at the all-cause dementia group alone in BioFINDER-2, with a similar trend observed for pTau217 in TRIAD." (PMID 38486040, 2024). "Our findings corroborate that an increase in peripheral GFAP and NfL levels can manifest over a decade prior to the diagnosis of dementia." (PMID 38735950, 2024). "More importantly, using the AD-GRS and APOE*E4 allele number, we identified potential shared genetic factors between dementia, GFAP, and NfL expression." (PMID 38735950, 2024). "Subsequently, we examined the levels of serum NfL, GFAP, and p-tau217 in other dementias, further exploring the effect of combining multiple markers on the differential diagnosis of AD from other dementias." (PMID 38615037, 2024). "Both biomarkers were elevated in more advanced clinical stages of the disease (i.e., in AD dementia compared with MCI due to AD: GFAP effect size 0.48, 95% CI 0.19–0.76, p = 0.0009; YKL-40 effect size 0.34, 95% CI 0.10–0.57, p = 0.0048)." (PMID 38986050, 2024). "Overall, we found that GFAP and NfL provided higher predictive values for dementia in participants < 65 years old compared to those ≥ 65 years old." (PMID 38735950, 2024). "A higher plasma GFAP was only associated with WMHV, and similar to plasma NfL, WMHV explained part of the association of plasma GFAP with dementia." (PMID 37530894, 2024). "Using GFAP and NfL alone achieved AUC in predicting dementia of 0.781 to 0.816, with corresponding C-Index of 0.792 to 0.829." (PMID 38735950, 2024). "In persistent delirium, GFAP and NfL were increased to levels comparable to concentrations seen in dementia." (PMID 39355007, 2024). "Our findings revealed that all plasma biomarkers were linked to the risk of progressing to clinically-diagnosed dementia of the Alzheimer's type (DAT), whereas only P-tau181, NfL, and GFAP showed associations with cognitive decline." (PMID 39253733, 2024). "Research has demonstrated that plasma GFAP can indicate when dementia will start to develop in PD patients with mild cognitive impairment (PD-MCI)." (PMID 39596444, 2024).
dementia (continued). "Immunological processes play a major role in the development of dementia, and GFAP is known as a marker of astrocyte reactivity or astrocytosis that is commonly found surrounding Aβ plaques." (PMID 38606661, 2024). "In our study, we harnessed UK Biobank data to explore the ties between GFAP, NfL, and various dementia types." (PMID 38735950, 2024). "When evaluating longitudinal changes, significant correlations were observed between the faster-annualized rate of change in GFAP and cognition, suggesting that the accumulation of peripheral GFAP reflects the severity of dementia." (PMID 38735950, 2024). "Given the emerging evidence linking GFAP and NfL levels to dementia prediction in healthy older adults, the increasing depressive symptoms reported by SCGs to spouses without dementia need close attention." (PMID 39297507, 2024). "This subset provided a unique opportunity to examine the relationship between the accumulation rates of peripheral GFAP and NfL and the rate of cognitive decline preceding dementia and early cognitive impairment." (PMID 38735950, 2024). "The UK Biobank, a large and well-characterized real-world cohort, offers a unique vantage point for probing the intricate relationships between GFAP, NfL, and dementia in dementia-free individuals." (PMID 38735950, 2024). "In this study, we show significant moderate positive correlations of finger-prick blood sampling and gold-standard plasma quantification of GFAP and NfL in a clinical cohort, comprising patients with dementia and TBI, as well as healthy volunteers." (PMID 38903933, 2024). "When adding GFAP and NfL to CAIDE and DRSm models, the predictive value significantly improved in predicting all-cause dementia and ADRD (NRI = 0.128 to 0.173)." (PMID 38735950, 2024). "Our findings underscore the potential utility of peripheral GFAP and NfL levels in the early diagnosis of dementia and suggest a potential role for anti-inflammatory therapies in the early phase of dementia." (PMID 38735950, 2024). "In our study with ~ 50,000 participants, we found robust correlations between peripheral GFAP and NfL expression with AD-GRS APOE*E4 alleles, suggesting shared genetic factors driving early neuroinflammation and neurodegenerative changes in dementia." (PMID 38735950, 2024). "Plasma GFAP, NfL and pTau 181 are promising biomarkers in the diagnosis of the prodromic stages and prognosis of dementia." (PMID 38654932, 2024). "Plasma GFAP predicted MCI-to-dementia conversion with an AUC of 0.90, higher than NfL, Tau and pTau181." (PMID 36759508, 2023). "In the present study, we found increased plasma GFAP levels in PD patients with dementia as well as MCI, compared to controls." (PMID 36759508, 2023). "In the subgroup of patients with PD-MCI who were clinically followed up for an average of 4.1 years, baseline plasma GFAP was significantly higher in patients who developed dementia than in those who remained stable with MCI." (PMID 36759508, 2023). "Although the relationship between plasma GFAP levels and clinical scores in PD patients remains incompletely understood, recent studies have demonstrated higher plasma GFAP levels in PD patients with dementia and mild cognitive impairment than in controls." (PMID 37480401, 2023). "We also investigated possible correlations between levels of GFAP and cognitive scores, as well as progression to dementia." (PMID 36759508, 2023). "In this study, we identify CSF GFAP as a prospective biomarker for forecasting the development of dementia in newly diagnosed untreated PD–NC patients over 8 years." (PMID 37475029, 2023). "Taken together, these findings imply that plasma GFAP holds promise as a viable biomarker in prognosticating the advancement to dementia in PD–MCI patients." (PMID 37475029, 2023). "Research has demonstrated the potential of plasma GFAP to forecast the progression to dementia in PD patients with mild cognitive impairment (PD–MCI)." (PMID 37475029, 2023).